RGP1 (RGP1 partner of RAB6A GEF complex)
Description:
The RIC1-RGP1 complex acts as a guanine nucleotide exchange factor (GEF), which activates RAB6A by exchanging bound GDP for free GTP and may thereby required for efficient fusion of endosome-derived vesicles with the Golgi compartment. The RIC1-RGP1 complex participates in the recycling of mannose-6-phosphate receptors.
Synonyms: KIAA0258
Tractability: Antibody: its Gene Ontology location is reachable by antibodies, with high confidence. PROTAC: ubiquitination databases record sites on it; its protein half-life has been measured.
Gene: Protein-coding gene on chromosome 9 (35,748,613 to 35,758,600, forward strand). Ensembl gene ENSG00000107185.
Subcellular location: Cytoplasm, cytosol; Membrane
Subcellular location (Human Protein Atlas): Cytosol; Plasma membrane
Pathways (Reactome):
Vesicle-mediated transport: Intra-Golgi traffic; RAB GEFs exchange GTP for GDP on RABs; Retrograde transport at the Trans-Golgi-Network
Gene Ontology:
Molecular function: guanyl-nucleotide exchange factor activity; protein binding; small GTPase binding
Biological process: negative regulation of protein catabolic process; positive regulation of GTPase activity; retrograde transport, endosome to Golgi
Cellular component: cytosol; membrane; protein-containing complex; Ric1-Rgp1 guanyl-nucleotide exchange factor complex; Golgi membrane; trans-Golgi network membrane
Genetic constraint (gnomAD): Loss-of-function variants: 28 observed, 43.63 expected, observed/expected ratio (o/e) 0.64, 90% interval 0.47 to 0.88. The upper end of that interval is the gene's LOEUF score, 0.88, which puts it in group 3 of 6, group 1 being the genes least tolerant of losing a copy. Missense variants: 415 observed, 511.19 expected, observed/expected ratio (o/e) 0.81, 90% interval 0.75 to 0.88. Synonymous variants: 212 observed, 206.39 expected, observed/expected ratio (o/e) 1.03, 90% interval 0.92 to 1.15.
Homologues: Orthologues: chimpanzee RGP1 (100% identical), macaque RGP1 (100% identical), pig RGP1 (99% identical), dog RGP1 (98% identical), mouse Rgp1 (97% identical), rat Rgp1 (97% identical), rabbit RGP1 (94% identical), guinea pig RGP1 (87% identical), tropical clawed frog rgp1 (69% identical), zebrafish rgp1 (66% identical), Drosophila melanogaster CG1116 (38% identical), Caenorhabditis elegans M01F1.9 (28% identical).
Diseases named in the same sentence as RGP1 in open-access papers:
RGP1 is named in the same sentence as 6 diseases in open-access papers, as found by Europe PMC text mining. Sharing a sentence is not in itself a finding about the gene and the disease. The quoted sentences say what the papers report.
scoliosis (1 paper, 2023). A congenital or acquired spinal deformity characterized by lateral curvature of the spine. "Deficiencies of RIC1 in CATIFA and Rgp1 in zebrafish models are consistent with type II collagenopathies, affecting collagen II secretion, and their common presentation includes scoliosis, cleft palate and a shorter jaw." (PMID 36843607, 2023).
adenocarcinoma of the (1 paper, 2019). "A mutation in RGP1 has been associated with adenocarcinoma of the large intestine." (PMID 30620740, 2019).
infection (1 paper, 2020). The state of being infected such as from the introduction of a foreign agent such as serum, vaccine, antigenic substance or organism. "Moreover, during the pathogen infection, RGP-1 also exerted anti-A." (PMID 32457762, 2020). "However, after infection, RGP-1 could affect the activities of LZM and AKP and reduce their functions significantly (P < 0.05), and these inhibitory effects followed a dose-dependent pattern." (PMID 32457762, 2020).
RGP1 also shares sentences with these, for which no sentence is quoted: Catifa syndrome (1 paper); Obesity (1); type II collagenopathies (1).